VTI1B (vesicle transport through interaction with t-SNAREs 1B)
Description:
SNAREs (soluble N-ethylmaleimide-sensitive factor-attachment protein receptors) are essential proteins for intracellular membrane fusion. SNAREs localized on opposing membranes assemble to form a trans-SNARE complex, an extended, parallel four-helix bundle whose assembly releases energy that drives membrane fusion. The core SNARE complex typically consists of four alpha-helical domains, three from target membrane SNAREs (t-SNAREs) and one from a vesicle SNARE (v-SNARE). On late endosomes, regulates trafficking from late endosomes to the lysosome (Probable).
Synonyms: VTI1; VTI1L; VTI2; VTI1-LIKE; v-SNARE; vti1-rp1
Tractability: Antibody: its Gene Ontology location is reachable by antibodies, with high confidence; UniProt predicts a signal peptide or a membrane-spanning region. PROTAC: ubiquitination databases record sites on it; its protein half-life has been measured.
Gene: Protein-coding gene on chromosome 14 (67,646,904 to 67,674,903, reverse strand). Ensembl gene ENSG00000100568.
Subcellular location: Early endosome membrane; Late endosome membrane; Lysosome membrane; Cytoplasmic granule; Recycling endosome membrane
Subcellular location (Human Protein Atlas): Golgi apparatus; Vesicles
Pathways (Reactome):
Hemostasis: Platelet degranulation
Gene Ontology:
Molecular function: chloride channel inhibitor activity; protein binding; SNAP receptor activity; SNARE binding
Biological process: autophagosome maturation; regulation of protein localization to plasma membrane; Golgi to vacuole transport; intra-Golgi vesicle-mediated transport; macroautophagy; retrograde transport, endosome to Golgi; vesicle fusion with Golgi apparatus; intracellular protein transport; vesicle-mediated transport
Cellular component: early endosome membrane; Golgi apparatus; late endosome membrane; lysosomal membrane; perinuclear region of cytoplasm; recycling endosome; recycling endosome membrane; SNARE complex; vesicle; endoplasmic reticulum membrane; ER to Golgi transport vesicle membrane; extracellular region; neuronal cell body; platelet alpha granule lumen; synaptic vesicle; cytoplasm; cytosol; endomembrane system; membrane; presynaptic endosome membrane
Genetic constraint (gnomAD): Loss-of-function variants: 15 observed, 26.01 expected, observed/expected ratio (o/e) 0.58, 90% interval 0.38 to 0.89. The upper end of that interval is the gene's LOEUF score, 0.89, which puts it in group 3 of 6, group 1 being the genes least tolerant of losing a copy. Missense variants: 282 observed, 296.23 expected, observed/expected ratio (o/e) 0.95, 90% interval 0.86 to 1.05. Synonymous variants: 99 observed, 110.42 expected, observed/expected ratio (o/e) 0.9, 90% interval 0.76 to 1.06.
Homologues: Orthologues: chimpanzee VTI1B (100% identical), pig VTI1B (94% identical), mouse Vti1b (93% identical), rat Vti1b (92% identical), macaque VTI1B (81% identical), dog RDH11 (80% identical), rabbit VTI1B (76% identical), zebrafish vti1b (58% identical), Drosophila melanogaster Vti1b (23% identical). Paralogues in human: VTI1A (30% identical), GOSR2 (16% identical).
Diseases named in the same sentence as VTI1B in open-access papers:
VTI1B is named in the same sentence as 9 diseases in open-access papers, as found by Europe PMC text mining. Sharing a sentence is not in itself a finding about the gene and the disease. The quoted sentences say what the papers report.
melanoma (1 paper, 2025). A malignant, usually aggressive tumor composed of atypical, neoplastic melanocytes. "Last, we analyzed the protein level of SMPD1 (ASM) and VTI1B in two melanoma cell lines overexpressing miR-16, using Western blot analysis." (PMID 40647495, 2025). "Transient overexpression of miR-16 resulted in a significant reduction in SMPD1 and VTI1B levels in melanoma cell lines." (PMID 40647495, 2025).
neuroblastoma (1 paper, 2022). Neuroblastoma (NB) is the most common solid, extracranial childhood tumor. "Vti1a and vti1b are expressed in every tissue and cell type analyzed including chromaffine cells and several neuroblastoma cell lines." (PMID 36419086, 2022).
parasite infection (1 paper, 2026). "VAMP7-VAMP8 as well as VAMP7-Vti1B double KO significantly reduced parasite infection and growth, with Vti1B playing a dominant role." (PMID 41972675, 2026).
prostate carcinoma (1 paper, 2025). A carcinoma that arises from epithelial cells of the prostate gland. "miR - 135b, significantly downregulated in prostate cancer, promotes bone metastasis by enhancing the migration capacity of prostate cancer cells, with PLAG1, JAKMIP2, PDGFA, and VTI1B identified as potential mediators." (PMID 40837012, 2025).
infection (5 papers, 2017 to 2026). The state of being infected such as from the introduction of a foreign agent such as serum, vaccine, antigenic substance or organism. "VAMP7 and Vti1B were localized to the PVM within 30 min post-infection, suggesting potential roles during invasion, while VAMP8 and Stx7 appeared later around 24 h post infection (hpi), coinciding with increased nutrient acquisition." (PMID 41972675, 2026).
cancer (1 paper, 2019). A tumor composed of atypical neoplastic, often pleomorphic cells that invade other tissues. "Other genes, such as CALCOCO2, RCAN2, ADI1, ECHS1, PLOD1 and VTI1B were associated with tumorigenesis or angiogenesis in some other cancers 33-35." (PMID 31632497, 2019).
nervous system disease (1 paper, 2020). "For instance, in OPC protein–protein interaction (PPI) network, proteins involved in Golgi vesicle transport (such as Vamp3, Golga7, Vti1b and Snx1), Cell redox homeostasis (such as Tnx2 and Gsr), nervous system disease (such as Got1, Gm2a, Apoe and Cst3) and other functions were identified." (PMID 32974003, 2020).
VTI1B also shares sentences with these, for which no sentence is quoted: tumor (2 papers); bacterial infection (1).